MIR3148 (microRNA 3148)
Synonyms: hsa-mir-3148; mir-3148
Gene: MicroRNA gene on chromosome 8 (29,957,272 to 29,957,348, reverse strand). Ensembl gene ENSG00000264788.
Homologues: Orthologues: chimpanzee MIR3148 (100% identical).
Diseases named in the same sentence as MIR3148 in open-access papers:
MIR3148 is named in the same sentence as 1 disease in open-access papers, as found by Europe PMC text mining. Sharing a sentence is not in itself a finding about the gene and the disease.
MIR3148 shares sentences with these, for which no sentence is quoted: gastric cancer (1 paper).